REG1A (regenerating family member 1 alpha)
Diseases named in the same sentence as REG1A in open-access papers (continued):
Sharing a sentence is not in itself a finding about the gene and the disease.
chronic kidney disease (1 paper, 2022). Impairment of the renal function secondary to chronic kidney damage persisting for three or more months. "We plan to continue collecting blood from patients with chronic kidney disease in subsequent studies to determine the specificity of RUNX3 and REG1A in the diagnosis of DKD." (PMID 35937821, 2022).
colon adenocarcinoma (1 paper, 2023). "Meanwhile, the expression profiles from TCGA datasets also pinpointed that REG1α in colon adenocarcinoma was considerably increased when compared with normal tissues." (PMID 37626036, 2023).
hepatoblastoma (1 paper, 2019). Hepatoblastoma (HB) is a malignant hepatic tumor and is the most common pediatric liver cancer. "It has been shown that there is a close relation between REG1A/3A proteins and β-catenin in development of hepatoblastoma." (PMID 31511432, 2019). "Indeed, a correlation has been found between up-regulation of REG1A/3A and β-catenin status in hepatoblastomas and scientists delineated that REG1A/3A are the downstream targets of the Wnt pathway during liver tumorigenesis." (PMID 31511432, 2019). "There have been other molecules that participate in Wnt/β-catenin triggered signaling pathway in hepatoblastoma including tumor necrosis factor-α (TNF-α), regenerating islet-derived 1 and 3 α (REG1A and 3A), substance P (SP)/neurokinin-1 receptor and PARP-1." (PMID 31511432, 2019).
intrahepatic cholangiocarcinoma (1 paper, 2016). A carcinoma that arises from the intrahepatic bile duct epithelium in any site of the intrahepatic biliary tree. "Furthermore, tissue expressions of Reg1A, Reg1B, and Reg4 could differentiate metastatic PDAC in the liver from intrahepatic cholangiocarcinoma with 92% sensitivity and 95% specificity." (PMID 27788482, 2016).
invasive carcinoma (1 paper, 2019). A carcinoma that is not confined to the epithelium, and has spread to the surrounding stroma.
lymph node metastasis (1 paper, 2023). "In summary, our results delineated that upregulated REG1α predicted lymph node metastasis, advanced TNM stage, and poor prognosis of CRC patients." (PMID 37626036, 2023). "CRC patients with lymph node metastasis showed higher expression of REG1α in serum." (PMID 37626036, 2023). "In the current study, we found that Regenerating islet-derived protein 1-alpha (REG1α) was significantly increased in both CRC tissues and serum, and positively associated with CRC patients’ lymph node metastasis, advanced tumor stage, and unfavorable prognosis." (PMID 37626036, 2023).
Obesity (1 paper, 2024). Accumulation of substantial excess body fat. "This analysis showed that some proteins, such as COL1A1, COL6A3, FABP4, LEP, LGALS1, and THBS4, are obesity-specific, and GDF15, LPL, MCFD2, REG1A, REG1B, and TCN2 are T2D-specific." (PMID 38732002, 2024).
primary Sjogren’s syndrome (1 paper, 2024). "In patients with primary Sjogren’s syndrome (SS), Reg1α induced by IL6/STAT pathway was detectable in salivary duct epithelial cells, and the salivary capacity was significantly decreased correlated with the presence of serum Reg1α autoantibody." (PMID 39857608, 2024).
cancer (26 papers, 2015 to 2025). A tumor composed of atypical neoplastic, often pleomorphic cells that invade other tissues. "Elevated levels of REG1A have been associated with poor prognosis in several types of cancers, as its expression can contribute to the aggressive behavior of cancer cells, including enhanced metastatic potential." (PMID 39000413, 2024). "This makes REG1A a potential biomarker for identifying high-risk cancer patients and a possible target for therapeutic intervention, aiming to inhibit its cancer-promoting activities." (PMID 39000413, 2024). "In the present study, to the best of our knowledge, we are the first to examine the REG1A variants in cancer by an extensive analysis of the six exons of REG1A using direct sequencing." (PMID 31541294, 2020). "Studies had seldom been conducted concerning the REG1A polymorphisms in relation to cancer." (PMID 31541294, 2020). "Reg1α has been reported to enhance radiosensitivity in cancer cells by activating c-Jun expression, thereby increasing susceptibility to anti-tumor treatments." (PMID 39857608, 2024). "In the realm of cancer biology, REG1A is particularly interesting due to its involvement in promoting cell growth, survival, and resistance to apoptosis, factors that are crucial for tumor progression and metastasis." (PMID 39000413, 2024). "Recently, intensive research unveiled that REG1α is remarkably highly expressed in various malignant tumors, including CRC." (PMID 37626036, 2023). "According to the immunohistochemical staining of normal cell-specific genes CTRB1 and REG1A, these cells showed rather gathered patterns adjacent to cancer cells within the tumor lesions, and their distributions varied between different patients." (PMID 35165277, 2022). "While REG1A expression increases with progression from PanINs to cancer, REG1B is already highly expressed in the earliest PanINs, which is in agreement with our data showing that REG1B is an earlier marker." (PMID 33301466, 2020). "Other five genes, including BSPRY, C8ORF47, FAM3B, HOOK1 and REG1A, were clustered in Model 16 and significantly decreased during cancer progression." (PMID 30598639, 2018). "REG1A has been reported to be expressed in various human cancers, and it plays crucial roles in the tumourigenesis of HCC36,37." (PMID 29330507, 2018). "The intensity of staining for Reg1A and Reg1B in these cancer cells was much stronger than that of Reg4, despite the fact that Reg4 had previously been reported as a biomarker of PDAC." (PMID 27788482, 2016). "However, almost all previous studies only examined the expression of REG1α in cancer and its correlation with clinical and pathological features." (PMID 37626036, 2023). "Other authors describe NEK2, MACC1, REG1A, KIF18A, RET, and TIP60 as possible PM-related cancer genes." (PMID 37629011, 2023). "Indeed, most of the patients’ tumor tissues contained REG1A- and CTRB2-positive cells, just around the cancer cells." (PMID 35165277, 2022). "The presence of REG1A is reported in extrapancreatic cancer types including non-small cell lung cancer, breast cancer, bladder cancer and colorectal sessile serrated adenoma." (PMID 31696115, 2019). "PDAC cancer tissues showed 22-fold and 6-fold increases of Reg1A and Reg1B mRNA levels than the adjacent non-neoplastic acinar tissues (P=0.025 and 0.016)." (PMID 27788482, 2016). "Immunohistochemically, the infiltrative PDAC cancer glands stained strongly positive for Reg1A and Reg1B, but negative for Reg3A/G." (PMID 27788482, 2016).
tumor (23 papers, 2016 to 2025). "We further utilized Wnt/β-catenin pathway-specific inhibitors XAV-939 to confirm the involvement of the Wnt/β-catenin axis on REG1α-stimulated glycolysis and malignant tumor phenotypes in CRC." (PMID 37626036, 2023). "On the contrary, silencing of REG1α retarded the tumor growth in vivo and decreased the tumor burden, while co-transfection with OE-MYC reversed the changes." (PMID 37626036, 2023). "Proliferating tumor cells in early stage PDAC express REG1A, REG1B, REG3A, and REG4 and throughout PDAC development." (PMID 31696115, 2019). "CCK-8 assay also displayed the tumor-promoting impacts of REG1α on the viability of CRC cells." (PMID 37626036, 2023). "However, Reg1A and Reg3A/G positive duct-like structures were observed in tumor-adjacent acinar areas." (PMID 27788482, 2016). "Furthermore, a high expression of REG1A in tumor cells is also a marker of poor prognosis in CRC." (PMID 39456726, 2024). "Exploration of the expression network indicated that inflammatory genes (CXCL8, CXCL3, PIGR, and RNASE1) and Wnt pathway genes (GAST, REG1A, TFF3, and ZG16B) are upregulated in tumor stem cells of UGICs." (PMID 35646860, 2022). "Some new tumor-specific markers for different pathologic types of RCC, such as SPOCK1, PTGIS, REG1A, CP and SPAG4 were identified and validated." (PMID 34722263, 2021). "Other members of the REG proteins family, i.e., REG1A and REG4, have been shown to be overexpressed in PDAC patients and to accelerate cell proliferation and tumor growth in vitro." (PMID 34099862, 2021). "Both REG1A and REG1B upregulation was demonstrated in precursor lesions, which resulted in an accelerated cell proliferation and tumour growth." (PMID 33301466, 2020). "High grade PDAC with low levels of Reg1A and Reg1B showed a statistically significant lower survival rate after tumor resection, when compared to those with low grade PDAC and high levels of Reg1A and Reg1B (P<0.0001, P<0.001 and P<0.001)." (PMID 27788482, 2016). "In addition, the experimental liver and lung metastasis models were also generated to evaluate the effects of REG1α and MYC on tumor cell metastasis." (PMID 37626036, 2023). "Thus, the results identified some new tumor-specific markers and verified SPOCK1, PTGIS, REG1A, CP and SPAG4 in different types of RCC." (PMID 34722263, 2021). "In this study, we firstly uncovered that REG1α played a pivotal role in regulating CRC cell proliferation, migration both in vitro and in vivo, and the upregulated REG1α in CRC patients was significantly correlated with lymph node metastasis, advanced tumor stage and worse prognosis." (PMID 37626036, 2023). "Recently, staining for CPA1 (carboxypeptidase A1) and REG1α (lithostathine-1-alpha) were found to have excellent sensitivity and specificity for PACC, essentially excluding the diagnosis if the tumor does not stain positively." (PMID 37538977, 2023). "REG1A is upregulated in naïve apCAFs, while PTGDS is upregulated in treated endothelial and iCAF cells; neither were observed in tumor cells." (PMID 35995947, 2022). "REG1A, REG3A, and REG3G expression is not observed in normal acini and ducts but is detectable in tumor-adjacent acinar areas." (PMID 31696115, 2019). "Immunostaining was also used to validate microarray analysis and found increased expression of S100A9 and REG1α in CA-CRC and in non-dysplastic tissue from patients with UC harbouring remote neoplasia, compared to patients with UC and without neoplasia and controls." (PMID 34200768, 2021).
infection (11 papers, 2012 to 2026). The state of being infected such as from the introduction of a foreign agent such as serum, vaccine, antigenic substance or organism. "Furthermore, PSP/reg1A levels did not correlate with infection/inflammation markers such as white cell count." (PMID 22808921, 2012).
renal disease (2 papers, 2022 to 2025). "A comparison of the area under the curve (AUC) profiles on multiple receiver operating characteristic curves of the DEGs in DKD and other renal diseases revealed that REG1A and RUNX3 had the highest specificity for DKD diagnosis." (PMID 35937821, 2022).
neurodegenerative disease (1 paper, 2022). A disorder of the central nervous system characterized by gradual and progressive loss of neural tissue and neurologic function. "The overexpression of Reg-1α in the brain in neurodegenerative diseases, and its reported limited cleavage associated with calcium homeostasis disturbance, has led us to focus on a particular class of proteases, the calpains." (PMID 35955718, 2022). "In the present study, we showed that Reg-1α can be cleaved in vitro by calpain-2, the calcium activated neutral protease, overexpressed in neurodegenerative diseases." (PMID 35955718, 2022). "We recently demonstrated that in the context of neurodegenerative disease Reg-1α increases Tau phosphorylation." (PMID 35955718, 2022). "Finally, the difference in fibril formation observed between the calpain- and trypsin-cleaved Reg-1α raises questions in the context of neurodegenerative diseases where calpains are overexpressed." (PMID 35955718, 2022).
REG1A also shares sentences with these, for which no sentence is quoted: hepatocellular carcinoma (3 papers); pneumonia (3); stomach cancer (3); Crohn disease (2); hepatic disease (2); liver cancer (2); type 2 diabetes (2); acute liver failure (1); acute pancreatitis (1); atherosclerosis (1); atopic dermatitis (1); Cirrhosis (1); co-infection (1); cyst (1); gastroenteropathies (1); gastrointestinal disease (1); Gestational Diabetes Mellitus (1); glioblastoma (1); infectious colitis (1); infectious disease (1); lymphopenia (1); metabolic disease (1); neuropathic pain (1); nosocomial infection (1); ovarian carcinoma (1); pancreatic acinar cell carcinoma (1); pancreatic adenocarcinoma (1); pancreatic diseases (1); rheumatoid arthritis (1); scrapie (1).
A further 3 diseases each share a sentence with REG1A in 1 paper.